HDAC5 (histone deacetylase 5)
Description:
In vitro, it deacetylates lysine residues on the N-terminal part of the core histones (H2A, H2B, H3 and H4). Histone deacetylation gives a tag for epigenetic repression and plays an important role in transcriptional regulation, cell cycle progression and developmental events. Histone deacetylases act via the formation of large multiprotein complexes. Involved in muscle maturation by repressing transcription of myocyte enhancer MEF2C. During muscle differentiation, it shuttles into the cytoplasm, allowing the expression of myocyte enhancer factors. Involved in the MTA1-mediated epigenetic regulation of ESR1 expression in breast cancer. Serves as a corepressor of RARA and causes its deacetylation. In association with RARA, plays a role in the repression of microRNA-10a and thereby in the inflammatory response.
Synonyms: HD5; KIAA0600; NY-CO-9; FLJ90614
Tractability: Small molecule: an approved drug acts on it; a structure with a bound ligand is known; a high-quality ligand is known; it belongs to a druggable protein family. PROTAC: UniProt records ubiquitination sites on it; ubiquitination databases record sites on it; its protein half-life has been measured; a small molecule that binds it is known. Other modalities: an approved drug acts on it.
Target class: HDAC class IIa; Histone deacetylase; Epigenetic regulator; Eraser
Chemical probes: pandacostat
Gene: Protein-coding gene on chromosome 17 (44,076,746 to 44,123,702, reverse strand). Ensembl gene ENSG00000108840.
Subcellular location: Nucleus; Cytoplasm
Subcellular location (Human Protein Atlas): Nuclear speckles; Cytosol; Golgi apparatus
Pathways (Reactome):
Disease: Constitutive Signaling by NOTCH1 HD+PEST Domain Mutants; Constitutive Signaling by NOTCH1 PEST Domain Mutants
Signal Transduction: NOTCH1 Intracellular Domain Regulates Transcription; Regulation of PTEN gene transcription
Developmental Biology: Differentiation of naive CD4+ T cells to T helper 2 cells (Th2 cells)
Gene expression (Transcription): Notch-HLH transcription pathway
Gene Ontology:
Molecular function: DNA-binding transcription activator activity; DNA-binding transcription factor binding; histone deacetylase activity; histone deacetylase binding; identical protein binding; protein binding; protein kinase C binding; protein lysine deacetylase activity; RNA polymerase II cis-regulatory region sequence-specific DNA binding; RNA polymerase II-specific DNA-binding transcription factor binding; transcription cis-regulatory region binding; transcription corepressor binding; chromatin binding; histone deacetylase activity, hydrolytic mechanism
Biological process: negative regulation of cell migration involved in sprouting angiogenesis; negative regulation of myotube differentiation; negative regulation of transcription by RNA polymerase II; positive regulation of transcription by RNA polymerase II; B cell activation; B cell differentiation; cellular response to insulin stimulus; inflammatory response; negative regulation of DNA-templated transcription; negative regulation of gene expression, epigenetic; regulation of myotube differentiation; cellular response to lipopolysaccharide; neuron differentiation; response to activity; response to cocaine; response to xenobiotic stimulus
Cellular component: cytoplasm; cytosol; nuclear speck; nucleus; histone deacetylase complex; nucleoplasm; protein-containing complex
Genetic constraint (gnomAD): Loss-of-function variants: 22 observed, 115.9 expected, observed/expected ratio (o/e) 0.19, 90% interval 0.14 to 0.27. The upper end of that interval is the gene's LOEUF score, 0.27, which puts it in group 1 of 6, group 1 being the genes least tolerant of losing a copy. Missense variants: 957 observed, 1,346.3 expected, observed/expected ratio (o/e) 0.71, 90% interval 0.67 to 0.75. Synonymous variants: 558 observed, 565.66 expected, observed/expected ratio (o/e) 0.99, 90% interval 0.92 to 1.06.
Homologues: Orthologues: macaque HDAC5 (99% identical), chimpanzee HDAC5 (96% identical), pig HDAC5 (96% identical), rabbit HDAC5 (95% identical), mouse Hdac5 (95% identical), rat Hdac5 (95% identical), dog HDAC5 (92% identical), guinea pig HDAC5 (88% identical), zebrafish hdac5 (71% identical), tropical clawed frog hdac5 (65% identical), Caenorhabditis elegans hda-5 (10% identical), Caenorhabditis elegans F43G6.4 (7% identical), and 1 more. Paralogues in human: HDAC4 (59% identical), HDAC9 (57% identical), HDAC7 (41% identical), HDAC6 (22% identical), HDAC1 (11% identical), HDAC2 (11% identical), HDAC10 (10% identical), HDAC3 (10% identical), HDAC11 (9% identical), HDAC8 (9% identical).
Diseases named in the same sentence as HDAC5 in open-access papers:
HDAC5 is named in the same sentence as 134 diseases in open-access papers, as found by Europe PMC text mining. Sharing a sentence is not in itself a finding about the gene and the disease. The quoted sentences say what the papers report.
breast carcinoma (42 papers, 2013 to 2025). "These outcomes suggest that dysregulations of HDAC2, HDAC4, and HDAC5 can collaborate with the development of tamoxifen resistance in ER+ breast cancer cells associated with miR-10b and miR-125a-5p deregulation." (PMID 34359587, 2021). "For clinical relevance, high SOX9 and HDAC5 expression are associated with lower survival rates in breast cancer patients treated with tamoxifen." (PMID 31690832, 2019). "Elevated mRNA or protein expression of HDAC5 led to an increased proliferation and invasiveness of a lung cancer cell line and was associated with inferior prognoses and clinical outcomes in patients with breast cancer and hepatocellular carcinoma." (PMID 38369747, 2024). "HDAC5 was positively associated with LSD1 levels in breast cancer cells and tissue specimens." (PMID 34178647, 2021). "High HDAC5 expression has been associated with poor prognosis in breast cancer (BC) tissue." (PMID 32050699, 2020). "Another study found that SFN facilitates lysine-specific demethylase 1 (LSD1) ubiquitination/degradation in a histone deacetylase 5-dependent (HDAC5) manner which inhibits breast cancer progression." (PMID 40013196, 2025). "At the molecular level, we discovered NUPR1 as a positive expression regulator of HDAC5 in breast cancer cells." (PMID 39991577, 2025). "Not only that, the researchers found that LC3-II increased over time when HDAC5 was depleted in breast cancer cells, and this effect was enhanced with the use of lysosomal inhibitors, suggesting that HDAC5 downregulation increased autophagic flux." (PMID 40260239, 2025). "We previously reported that HDAC5 (an epigenetic regulator) upregulation promotes estrogen independence and Tamoxifen resistance in ER+ breast cancer cells 15; however, the expression regulation of HDAC5 was unclear." (PMID 39991577, 2025). "HDAC2 is associated with poor survival and relapse of cancer, HDAC3 promotes oncogenesis and is a good target for therapeutics, HDAC5 is known to increase the stemness of breast cancer cells, and HDAC7 protein is associated with reoccurrence of breast cancer." (PMID 40426890, 2025). "In human breast cancer, HDAC5 stimulates proliferation, invasion, and migration, making it a possible therapeutic target and prognostic indicator." (PMID 40077783, 2025). "HDAC5-mediated SOX9 deacetylation induces SOX9 nuclear localization in HR-positive breast cancer, and HDAC5 overexpression promotes cell growth under tamoxifen exposure." (PMID 37568822, 2023). "Accordingly, HDAC5 expression has been related with worse prognosis and the presence of metastasis in breast cancer." (PMID 36901692, 2023). "For instance, overexpressed HDAC5 is reported in breast cancer, lung cancer, HCC, pancreatic neuroendocrine cancer, and colorectal cancer (CRC)." (PMID 36910848, 2023). "And its function will also change due to the different subtypes in the same tumor, ER status determines the effect of HDAC5 on the vulnerability to CDK4/6 inhibitors in breast cancer." (PMID 35265200, 2022). "Levels of HDAC4 and HDAC5 have been reported as transcriptionally overexpressed in human breast cancer compared to normal or benign breast tissue." (PMID 36466344, 2022). "HDAC5 increased the stemness of human breast cancer stem cells through inhibiting the binding of the Runt-related transcription factor 3(RUNX3)/p300 complex to the promoter of target genes." (PMID 34178647, 2021). "Tamoxifen is a first-line treatment for breast cancer, HDAC5 deacethylated SOX9 and made it localized in the nucleus, which was responsible for tamoxifen resistant in breast cancer." (PMID 34178647, 2021). "In turn, HDAC5 promoted SOX9 nuclear localization via interaction with its HMGB domain (amino acids 1–181) in estrogen receptor-positive breast cancer cells." (PMID 34178647, 2021). "HDAC5 expression was also elevated in estrogen-independent breast cancer cells and induced tamoxifen resistance via the miR-125a-5p/specificity protein 1 (Sp1)/survivin axis." (PMID 34178647, 2021).
breast carcinoma (continued). "Elevated HDAC5 expression is frequently observed in the luminal A and B subtypes of breast cancer, and HDAC5 silencing suppressed breast cancer cell motility and invasion." (PMID 34178647, 2021). "Public dataset analysis (GEO: GSE9574) revealed that the expressions of HDAC5 in tumour tissues of ER+ breast cancer patients were higher than those in the epithelium adjacent to breast tumours." (PMID 31690832, 2019). "Similar results for HDAC5 expression were found in breast cancer tissue samples, hepatocellular carcinoma tissue samples, and melanoma cells in vitro." (PMID 30321986, 2018). "HDAC5 mRNA and protein expression in breast cancer are known to promote metastasis and to be important negative prognosticators of survival." (PMID 29897996, 2018). "SFN treatment blocks the upstream transcription factor 1 (USF1) of HDAC5 inhibits the breast cancer cell lines." (PMID 30445746, 2018). "When HDAC5 was depleted in breast cancer cells, LC3-II increased over time, and this effect was enhanced by the use of a lysosomal inhibitor, indicating that HDAC5 downregulation increased autophagic flux." (PMID 25915736, 2015). "Previous studies have indicated that histone deacetylase inhibitors (HDACi) can reduce tumor formation and induce intrinsic apoptosis in breast cancer cells by targeting HDAC5, which relies on the activation of the intrinsic apoptosis pathway involving caspase 9/3 signaling." (PMID 40781327, 2025). "In a pilot study, we found that the MCF7 cell line-derived, ER+, estrogen-independent, and tamoxifen-resistant, MCF7-TamC3 breast cancer cells exhibit increased expression of two epigenetic regulators, HDAC5 and HDAC2, compared to the parental ER+ MCF7 breast cancer cells." (PMID 39991577, 2025). "In prostate and breast cancer cells, HDAC5 KD promotes resistance to palbociclib." (PMID 39624079, 2024). "Because HDAC5 has been shown to mediate tamoxifen resistance in HR-positive breast cancer, it may be worth developing and testing class II HDAC inhibitors for overcoming resistance in advanced-stage HR-positive breast cancer." (PMID 37568822, 2023). "Knockdown of HDAC5 also induced G1 cell cycle arrest, which hindered breast cancer proliferation." (PMID 34178647, 2021). "In addition, the transcription factor C-MYC directly promotes the expression of HDAC5 in tamoxifen resistant breast cancer cells." (PMID 31690832, 2019). "Targeting C-MYC/HDAC5/SOX9 axis might be beneficial for the discovery of new strategies for ER+ breast cancer therapy." (PMID 31690832, 2019). "Both LSD1 and histone deacetylases (HDACs) facilitate breast cancer proliferation, and interestingly, HDAC5 could promote the stability of USP28." (PMID 29415985, 2018). "We next examined the role of HDAC2 and HDAC5 in the survival of ER+ breast cancer cells." (PMID 29326587, 2017). "Collectively, these results suggest that aberrant expression of HDAC2 and HDAC5 may affect the effectiveness of hormone therapy in patients with ER+ breast cancer." (PMID 29326587, 2017). "Interestingly, miR-125a-5p not only targets HDAC4 down-regulation but also decreased the expression of HDAC5 in human breast cancer." (PMID 25504437, 2015). "Moreover, recent studies demonstrated that HDAC5 was up-regulated in several types of cancers, such as acute lymphoblastic leukemia, medulloblastoma, and breast cancer." (PMID 24191246, 2013). "Among the 65 potential transcription factors, we speculated that C-MYC may be the key transcription factor for promoting HDAC5 transcription, as the expression of C-MYC is positively correlated with HDAC5 expression indicated by analysis with the public dataset GSE9574 in ER+ breast cancer." (PMID 31690832, 2019). "Therefore, C-MYC/HDAC5/SOX9 axis is essential for promoting tamoxifen resistance in breast cancer." (PMID 31690832, 2019).
breast carcinoma (continued). "Therefore, targeting USP28 may tune down the HDAC5/LSD1-mediated epigenetic process that drives breast cancer development and progression." (PMID 29415985, 2018). "However, little is known regarding the specific role of HDAC5 in breast cancer (BC)." (PMID 27177225, 2016). "Other miRNAs include miR-9-5p (HDACs in gastric cancer), miR-101 (EZH2 in glioblastoma), miR-22 (TIP60 and HDAC4 in breast cancer), and miR-125 (HDAC4 and HDAC5 in breast cancer)." (PMID 40761244, 2025). "We also note that TMP195, a first-in-class highly selective class II HDAC inhibitor, has shown potent activity in breast cancer mouse model studies, making it an attractive candidate to test in JMML patients who display increased HDAC5 and HDAC9 activity." (PMID 37958378, 2023). "For example, USF1 transactivated HDAC5 by physically binding to the HDAC5 promoter at −356 to −100 bp, thereby increasing the stability of LSD1 to induce chemoresistance of breast cancer." (PMID 34178647, 2021). "At the same time, histone deacetylase 5 (HDAC5) enhances USP28 stability and facilitates breast cancer cell proliferation in a LSD1-dependent manner." (PMID 34575114, 2021). "In summary, in the present study we identified HDAC5, whose transcription promoted by C-MYC, is essential for SOX9 deacetylation and nuclear localisation in tamoxifen-resistant breast cancer." (PMID 31690832, 2019). "For clinical relevance, breast cancer patients with tamoxifen treatment expressing elevated SOX9 and HDAC5 have a worse overall survival." (PMID 31690832, 2019). "Collectively, these results suggest that HDAC5 deacetylates SOX9 to maintain its nuclear localisation, which drives tamoxifen resistance in breast cancer." (PMID 31690832, 2019). "In this study, we demonstrated the indispensable role of HDAC5 in mediating the deacetylation and nuclear localisation of SOX9 in tamoxifen resistant breast cancer cells." (PMID 31690832, 2019). "HDAC5 and SOX9 are related to the poor survival rates in endocrine-therapy-treated ER+ breast cancer." (PMID 31690832, 2019). "Signaling between HDAC5 and lysine-specific demethylase 1 (LSD1) facilitates the abnormal growth of breast cancer cell lines." (PMID 30445746, 2018). "HDAC2 siRNA and HDAC5 siRNA also promoted the death of MCF7, MCF7-TamC3, and the ER+ tamoxifen-sensitive ZR-75-1 breast cancer cells." (PMID 29326587, 2017). "Further molecular analysis revealed that HDAC2 and HDAC5 positively modulates the expression of survivin, and negatively regulates the expression miR-125a-5p, in ER+ MCF7, MCF7-TamC3, and ZR-75-1 breast cancer cells." (PMID 29326587, 2017). "In this study, we found that the MCF7-derived, ER+, estrogen-independent, tamoxifen-resistant MCF7-TamC3 breast cancer cells exhibit increased expression of HDAC2 and HDAC5 as compare to the estrogen-dependent, tamoxifen-sensitive MCF7 cells." (PMID 29326587, 2017). "HDAC5 (histone deacetylase 5) and LSD1 coordinately overexpressed in breast cancer." (PMID 40028036, 2025). "We previously demonstrated that HDAC5 negatively regulates the expression of the microRNA molecule, miR-125a-5p, and the overexpression of miR-125a-5p decreases the expression of ERBB2 in ER+ breast cancer cells." (PMID 39991577, 2025). "Notably, the current study reveals a new role of Nuclear Protein 1 (NUPR1/P8/COM1) in regulating the expression of HDAC5, ERBB2 (and the survival reliance switch from estrogen to EGF) and BIRC5 (a well-known oncogene) in breast cancer cells." (PMID 39991577, 2025). "The qPCR and the western blot analysis results revealed that NUPR1 positively regulates the expression of the epigenetic regulator HDAC5, the anti-apoptotic molecule BIRC5, and the mitogenic receptor ERBB2 in MCF7-TamC3 and the ERBB2-enriched subtype like SK-BR-3 breast cancer cells." (PMID 39991577, 2025). "In addition, HDAC5 is regulated by C-MYC, which directly controls its expression in breast cancer cells." (PMID 39624079, 2024).
breast carcinoma (continued). "The expression of HDAC5 and lysine-specific demethylase 1 (LSD1) was elevated in breast cancer, and HDAC5 enhanced the LSD1 protein stability and reduced the nuclear level of H3K4me1/me2 in breast cancer cells." (PMID 34395273, 2021). "And silencing either HDAC4 or HDAC5 was able to promote the nuclear import of SerRS as well, strongly indicating that HDAC4 and HDAC5 regulate the acetylation of SerRS at lysine 323 and hence its nuclear localization in breast cancer cells." (PMID 34400610, 2021). "Thus, HDAC5 and SOX9 expression levels are crucial factors related to the overall survival in endocrine-therapy-treated ER+ breast cancer." (PMID 31690832, 2019). "In contrast, the role of HDAC2 and HDAC5 in the development of hormone therapy resistance in ER+ breast cancer has not yet been studied in details." (PMID 29326587, 2017). "Dysregulation of HDAC2 and HDAC5 can be found in ER+, estrogen-independent, tamoxifen-resistant breast cancer cells and high expression of HDAC2 correlates with poor clinical outcomes in ER+ tamoxifen-treated breast cancer patients." (PMID 29326587, 2017). "In this study, we found that ER+, hormone-independent, tamoxifen-resistant MCF7-TamC3 cells exhibit increased expression of HDAC2, HDAC5, and survivin, but show decreased expression of miR-125a-5p, as compared to the parental tamoxifen-sensitive MCF7 breast cancer cells." (PMID 29326587, 2017). "Despite not reaching statistical significance, high HDAC5 expression levels also correlate with poor overall survival (HR = 1.85) in tamoxifen-treated ER+ breast cancer patients." (PMID 29326587, 2017). "We noticed that the ERBB2 (HER2)-enriched subtype-like [ER-, ERBB2 (HER2)+/high] SK-BR-3 breast cancer cells express a large amount of the nucleic NUPR1 protein endogenously, as compared to MCF7 and MCF7-TamC3 cells, and the si-NUPR1 treatment also decreased the expression of HDAC5 in SK-BR-3 cells." (PMID 39991577, 2025). "Furthermore, HDAC5 mRNA and protein have been detected in the blood of patients with CRC and breast cancer, but not in that of healthy subjects or patients with nonrecurrent cancer, suggesting that circulating HDAC5 may serve as a potential biomarker for cancer diagnosis and prognosis." (PMID 34178647, 2021). "In addition, HDAC5 promoted breast cancer development and progression in a LSD1-dependent manner 42, however, there were no direct evidence that USP28 was involved in breast cancer progression in the study." (PMID 33664871, 2021).